MICB (MHC class I polypeptide-related sequence B)
Diseases named in the same sentence as MICB in open-access papers (continued):
Sharing a sentence is not in itself a finding about the gene and the disease.
tumor (continued). "We observed a significant downregulation of NKG2D ligands, such as MICA, MICB and ULPB1, 2, and 3 following BET/JQ1treatment of the human tumor cells with similar findings noted in mouse N2a treated cells as well (Ulbp1, Rae1a and Rae1b)." (PMID 40552293, 2025). "NK cells exert their cytotoxic effects primarily through activating receptors, such as NKG2D, which recognizes stress-induced ligands on the surface of tumor cells, such as MICA, MICB, and ULBPs." (PMID 40076725, 2025). "Meanwhile, NKG2D on exosomes facilitates tumor cell targeting by recognizing stress-induced ligands such as MICA, MICB, and ULBP, which are commonly overexpressed in tumors." (PMID 40076725, 2025). "During tumor immunosurveillance, the expression of MICA, MICB, and ULBP on tumor cells can be recognized by NKG2D, a NK-like activating receptor (NKR) expressed on γδT cells, particularly in Vγ9Vδ2 subset." (PMID 40226616, 2025). "As MICA/B expressing tumor cells are more sensitive to NK cytotoxicity, many epigenetic drugs are found to increase MICA and MICB expression and exert antitumor effects." (PMID 38882209, 2024). "Among these ligands, MICA and MICB are well characterized, with MICA more abundantly expressed in tumor cells." (PMID 39335190, 2024). "NKG2D plays an important role in the anti-tumor activity of NK cells due to its ability to bind to MHC-I-chain-related molecules, such as MICA, MICB, and the UL16-binding proteins (ULBPs)." (PMID 39339180, 2024). "MICA and MICB are homologous proteins of MHC class I molecules and are frequently and abundantly expressed on the surface of tumor cells and are reported to bind to the NK cell receptor NKG2D." (PMID 37508520, 2023). "A third recently described mechanism by which tumour cells can reduce MICA and MICB expression involves neddylation." (PMID 37626965, 2023). "Apart from TCR ligands, ligands induced on epithelial and tumor cells via stress or structural damage, including MICA, MICB and UL16-binding proteins (ULBPs), are recognized by NKG2D on both intraepithelial Vδ1 and circulating Vδ2 cells." (PMID 38274800, 2023). "Tumor-derived EVs also express the surface ligands of NKG2D, such as ULBP-2 and MICA/MICB, acting as negative regulators of NKG2D on NK cells in a dose-dependent manner and impairing cytotoxicity against tumor cells." (PMID 37175226, 2023). "It has been reported, contrary to membrane-bound form, that the soluble form of MICB induces downmodulation of NKG2D expression on systemic and tumor-infiltrated NK and T-cells and thus results in its functional impairment." (PMID 38139416, 2023). "UL16-binding protein (ULBP), MHC class I-related chain A (MICA) and B (MICB) are NKG2D ligands, commonly overexpressed on tumor cells." (PMID 37090711, 2023). "We found the mRNA expression level of MICA, MICB, ULBP1, ULBP2, ULBP4, and ULBP5 was significantly higher in tumor tissues than that in adjacent normal tissues, whereas ULBP3 expression was lower in tumor tissues compared to adjacent normal tissues." (PMID 36210637, 2023). "Unfortunately, tumor cells have various mechanisms to evade immune surveillance, and one of them is cleavage of MICA/MICB from the cell membrane using surface proteases." (PMID 38033491, 2023). "Tumor cells and primary MM cells treated with DRd for 24 h showed significantly increased expression of MICA, MICB, ULBP1, ULBP2, and Fas receptor compared to Rd or untreated tumor cells (all p < 0.0001)." (PMID 36385211, 2023). "Several other studies reported the role of tumor miRNAs in controlling the expression of other NKG2D ligands, including MHC class I polypeptide-related sequence B (MICB), UL16 binding protein (ULBP), and other immunological mediators." (PMID 36248881, 2022). "In these immunostimulatory marker genes, CD276, MICB, NT5E, PVR and ULBP1 had a significantly positive correlation with RRM2 expression in most tumor types." (PMID 35740608, 2022).
tumor (continued). "It has been shown that tumour cells and CAFs escape immune cell attack by expressing high levels of PD‐L1 and PD‐L2, and shedding NKG2D ligands (MICA, MICB and ULBP1‐6) from the cell surface through proteolytic cleavage." (PMID 35731974, 2022). "Several different HDACIs have also been shown to increase NK cell killing of tumor cells by upregulating the stress-inducing ligands, such as MICA, MICB, and ULBP1-3, in tumor cells from many different solid malignancies." (PMID 35140720, 2022). "NKG2D-expressing Vδ1+γδ T cells can be activated by stress-induced MHC class I chain-related antigens A and B (MICA/MICB) and UL16-binding proteins (ULBP16), which are upregulated in tumor cells contrary to healthy cells." (PMID 36499125, 2022). "Studies have shown that MICA and MICB (stress-induced proteins as NKG2D ligands) are upregulated in hepatocytes from chronic liver diseases and tumor cells from HCC lesions." (PMID 36611926, 2022). "Similar to Vδ2+ γδ T cells, the NKG2D-expressing Vδ1+ γδ T cells can be activated by stress-inducible MICA/MICB and ULBP1–6 family proteins, which are frequently upregulated in tumor cells." (PMID 35880177, 2022). "Although all of them seem to be over-expressed by different tumor cells, more knowledge has been obtained for MICA and MICB." (PMID 34394116, 2021). "MiR-10b directly targets MICB, the stress-induced ligand of NKG2D receptor, expressed by tumor cells, thus impairing NK-mediated recognition and elimination of tumor cells." (PMID 33924670, 2021). "We therefore developed a novel mAb directed against both MICA and MICB, named Mia4, which specifically stained the MICA and MICB proteins on formalin-fixed, paraffin-embedded tumor tissue sections." (PMID 35967081, 2021). "NKG2D ligands (MICA, MICB, and ULBP1‐6) are expressed on stressed or tumor cells, favoring their destruction." (PMID 34323406, 2021). "For example, MICB is defined as the casual gene of CESC, PRAD, and UCEC, but showed a high correlation with the tumor purity in four cancer types (KIRC, KIPP, LUAD, and MESO), which were not included in the selection step." (PMID 35003220, 2021). "NKG2DL, like the MHC class I chain-related protein A and B (MICA and MICB) or the UL 16 binding protein 1–6 (ULBP1–6), are highly expressed on the surface of stressed cells but also by tumor cells." (PMID 33800301, 2021). "It has been previously shown that they enhance NK cell-mediated tumor cell targeting by upregulating the stress-inducing ligands MICA, MICB, and ULBP1-3 in tumor cells permitting a more efficient killing of tumor cells." (PMID 34957134, 2021). "The activating receptor NKG2D induces NK cell-mediated killing of metastasizing tumor cells by recognition of the stress-induced ligands MICA, MICB, and ULBP1-6." (PMID 33424862, 2020). "As an essential receptor for the activation of NK cells, NKG2D is blocked by many ligands (e.g., MICA, MICB, and ULBP1–6) upregulated in tumor cells as a result of abnormal cellular stress in the TME." (PMID 32762681, 2020). "Since NK cells efficiently recognize and kill tumor cells bearing NKG2D ligands, a reduction of MICB on the tumor surface potentially inhibits the “danger signals” that alerts the innate immune system, and therefore reduces tumor elimination." (PMID 32582365, 2020). "Finally, we found that the increased γδ T cell abundance in the TME was associated with upregulation of BTN family proteins and the NKG2D ligand MICB in tumor cells, indicating that the activation of γδ T cells may be associated with BTN family proteins and MICB." (PMID 33101298, 2020). "TGF-β appears to act simultaneously on NK cells and tumor cells via miR-183, with the result to inhibit the NK cells' anti-tumor activity by down-regulating DAP12, in NK cells, and NKG2D ligands (MICA and MICB), in cancer cells." (PMID 32161594, 2020).
tumor (continued). "Alternative tumor immune escape mechanisms include upregulation of HLA-E on the tumor cell surface and release of soluble NKG2D ligands, such as MICA and MICB." (PMID 32903482, 2020). "The increased expression of MICA and MICB on CSC targets thereby enhanced NK cell mediated killing in vitro and ex vivo from both human primary tumor and patient-derived xenograft samples." (PMID 30646520, 2019). "Compared to non-tumor tissues (N), a variety of factors like TGF-β1, TGF-β2, HMGB1, PVR, nectin-2, galectin-9, PD-L1, PD-L2, and MICA/MICB were significantly higher in the tumor tissue (T)." (PMID 31234517, 2019). "It was demonstrated that NKG2D ligands (MICA, MICB, and ULBP) carried by tumor-derived EVs bound to the inhibitory receptor, NKG2D, on the surface of NK cells, with delivering of inhibitory signals and blocking of anti-tumor cytotoxicity of NK cells." (PMID 31680949, 2019). "We supported this finding by demonstrating decreased NK cell recognition and reactivity to tumour cells that were neutralised with antibodies against the NKG2DL, MICA and/or MICB." (PMID 30908480, 2019). "As the biology of ULBP4 (RAET1E), ULBP5 (RAET1G), and ULBP6 (RAET1L) and their role in tumor immunity is poorly understood, we will focus on the well-studied five ligands MICA, MICB, ULBP1-3." (PMID 30254634, 2018). "Recently, a new antibody was developed to prevent the shedding of both MICA and MICB in order to restore NKG2D receptor activity and induce better killing of tumor cells by inducing antibody dependent cellular cytotoxicity (ADCC)." (PMID 30254634, 2018). "These NKG2DLs on tumor cells include MHC class I-related chains A and B (MICA and MICB) and proteins in the UL16-binding protein family (ULBP1-6, mainly ULPBP1–3)." (PMID 29910819, 2018). "The tumour secretes factors such as soluble MICA, MICB, and vesicles containing ULBP3, all of which impair NK cell cytotoxic ability, facilitating immune evasion." (PMID 28668076, 2017). "For example, MICA and MICB are recognized by the NK cell activating receptor NKG2D, triggering cytotoxicity against the NKG2D ligand-carrying tumor cell." (PMID 27843441, 2016). "The use of sections of the whole tumor also allowed us to determine the expression pattern of MICA and MICB." (PMID 26902929, 2016). "An enhanced sensitivity of tumor cells to NK cell-mediated lysis has been attributed to an increased membrane expression density of the NKG2D ligands MICA and MICB." (PMID 25854583, 2015). "Human NKG2D recognizes several structurally related ligands (NKG2DLs) on tumor cells from various cytological origin, including the MHC class I chain-related protein A (MICA), MICB, and the UL16-binding proteins (ULBPs)." (PMID 25933805, 2015). "In T47D tumor cells which lack a MICA membrane expression, the MICB expression was found to be strongly reduced upon treatment with NZ28." (PMID 25854583, 2015). "At the post-translational level, NKG2D ligands such MICA, MICB, and ULBPs were found to be cleaved from the cell surface by proteases ADAM10/17 and MMP14 and in some cases by tumor-derived exosomes." (PMID 25788898, 2015). "The importance of ligands expression for tumor cell recognition by NK cells is a key factor for anti-tumor immune response, as illustrated by the strong prognostic value of MICA/MICB, RAET1G, and ULBP2 expression in colorectal cancer and breast cancer." (PMID 24715892, 2014). "NKG2D, one of the best characterized NK cell activating receptors, can promote tumor lysis upon recognition of MICA, MICB or the ULBPs." (PMID 21631944, 2011). "It would be interesting to determine if the simultaneous expression of MICA, MICB and the NKG2D receptor is present in different types of virus-infected and tumor cells." (PMID 21477352, 2011). "NKG2D encodes for a lectin-related protein expressed as a homodimer and functioning as an activating receptor for ligands often expressed by tumor cells, namely, class I MHC-related molecules such as MICA, MICB, and UL16-binding proteins." (PMID 21138560, 2010).
tumor (continued). "In order to further research how Anti-MICB-CAR-NK promotes tumor cell apoptosis, treat PANC-1 tumor cells for 24 h with NC-NK cells, non-transduced NK (NT-NK), NT-NK supernatant + NK cells, Anti-MICB-CAR-NK supernatant + NK cells, and Anti-MICB-CAR-NK cells." (PMID 41516373, 2026). "NK and Anti-MICB-CAR-NK significantly decreased tumor growth by 27.28% and 46.38%, respectively (with no obvious effects on body weight)." (PMID 41516373, 2026). "The rapid clearance of PANC-1 cells may be attributed to the ability of Anti-MICB-CAR-NK cells and free Anti-MICB-scFv to block MICB detachment from the tumor cells, allowing NKG2D to bind to MICB and activate tumor killing in vivo." (PMID 41516373, 2026). "MICA and MICB are not expressed or expressed at a low level in normal tissue cells but are highly expressed on the surface of various tumor cells." (PMID 40563539, 2025). "Additionally, MICA/MICB and NKG2D are a known receptor–ligand pair expressed in tumor cells and NK cells, respectively." (PMID 40430484, 2025). "In another study, the high-affinity monoclonal antibody RDM028 targeting the α3 domains of MICA and MICB was also reported to have inhibitory effects on the exfoliation of MICA and MICB, enhance the anti-tumor activity of NK cells, and promote the interaction between MICA/B and NKG2D." (PMID 40563539, 2025). "Genes such as GATA4, CLDN23, MICB, MFHAS1, and BMPR2 were enriched in multiple signatures including estrogen response, coagulation, DNA repair, tumor-promoting inflammation, immune evasion, angiogenesis, sustained proliferative signaling, resistance to cell death, and metastasis." (PMID 40863222, 2025). "KCNN4 has been shown to have positive correlations with several costimulatory molecules (CD276, CD40, CD70, CD80, CD86), immune signaling receptors (IL2RA, MICB, NT5E), and multiple TNFRSF family members, suggesting its involvement in immune modulation, inflammation, and tumor‐immune interactions." (PMID 40952239, 2025). "In tumor cells, immune stimulation revealed an interplay of both immune activating and inhibitory signals, including up-regulation in immune-activating signals such as the FAS death receptor gene and the NK-activating ligand MICB." (PMID 39475596, 2024). "However, the majority of human solid tumors express high levels of NKG2D ligands, in particular MICA and MICB molecules, suggesting that tumors developed mechanisms to evade NKG2DL-NKG2D mediated anti-tumor immunity." (PMID 38255301, 2024). "Interestingly, in the TCGA‐LIHC and Guilin cohort, there was a significant difference in the expression of MICA, MICB, and ULBP1‐5 between HCC tumor and adjacent non‐tumor tissues." (PMID 36210637, 2023). "NKG2D ligands (class I MHC-like proteins, including MHC class I-related chain A (MICA) and MICB) are mainly present in tumor cells, and not normal cells." (PMID 38033491, 2023). "Moreover, previous studies have shown that MICA and MICB, members of the MHC-I family, are frequently highly expressed in tumor cells and can be proteolytically shedded by tumors as an important immune evasion mechanism avoiding the recognition of NK cells." (PMID 37427097, 2023). "Similarly, NK cell-tumor cell-interaction is disturbed since expression of NKG2D is downregulated by soluble MICA and MICB released from adjacent tumor cells." (PMID 37684704, 2023). "In addition, the platelet coating on tumor cells reduces the surface expression of NKG2D ligands, including MHC class I chain–related proteins A and B(MICA and MICB) on tumor cells, impairing the “induced self” recognition of NK cells." (PMID 37153586, 2023). "Released soluble MICA (sMICA) and soluble MICB (sMICB) can thereafter bind to NKG2D and induce its down-modulation and degradation, subverting NKG2D-dependent effector functions of NK cells and facilitating tumor immune escape." (PMID 34394116, 2021).
tumor (continued). "Interestingly, tumor cells are able to shed MICA and MICB from their surface, which can bind to the cell surface NKG2D and provokes an internalization of NKG2D into NK cells." (PMID 33800301, 2021). "However, to evade NK cell recognition and to reduce the NKG2D-mediated NK cell activation, tumor cells shed MICA and MICB from their surface." (PMID 34203391, 2021). "Indeed, some ADAMs are expressed in malignant tumors and participate in cancer pathology with ADAM10 and ADAM17 playing a prominent role for this mechanism of tumor immune-evasion by controlling MICA and MICB." (PMID 33789714, 2021). "In addition, tumor-secreted enzymes are able to shed the activating ligands B7-H6, MICA, MICB and ULBP2 from NK cells through the activity of metalloproteases." (PMID 33802954, 2021). "Specifically, miR-10b and miR-20a have been found to downregulate MHC Class I chain-related A and B (MICA and MICB, respectively) ligands of the natural killer (NK) activating receptor, NKG2D, thus resulting in the suppression of innate immunity and subsequent tumor growth." (PMID 33924670, 2021). "The best characterized NK cell-activating receptor playing a prominent role in tumor immunosurveillance is NKG2D, whose ligands (MICA, MICB, ULBP1-6) are frequently induced on the surface of tumor cells in response to different types of cellular stress typical of a neoplastic transformation." (PMID 31948072, 2020). "However, tumor cells also express molecules that activate NK cells, e.g., MHC class I polypeptide-related sequence A (MICA) and MICB, supporting the use of NK cells as anti-cancer agents." (PMID 32762681, 2020). "In the context of tumor-immunosurveillance, pADAM10 has not only been identified as sheddase of canonical substrates on platelets, but also to be involved in cleavage of the stress-induced NKG2D ligands (NKG2DL) MICA, MICB and ULBP2 from the surface of tumor cells." (PMID 32117229, 2020). "Given the role of platelets in regulating tumour cell expressed ligands and NK cell expressed receptors in the NKG2D-MICA/MICB system, we hypothesised that the CD226/CD96-CD112/CD155 axis would be regulated in a similar manner." (PMID 30908480, 2019). "In addition, it was demonstrated that tumor cells released the NKG2D ligands, MICA and MICB, in a soluble form by proteolytic shedding from the tumor cell surface by metalloproteases and protected tumor cells from cytolysis if they were NKG2DL-positive." (PMID 30845699, 2019). "By treating releasate from platelet cloaked tumour cells that contained platelet soluble factors plus tumour cell soluble factors, with neutralising antibodies to MICA and MICB the suppression of NKG2D, degranulation and pro-inflammatory cytokine production was partially rescued." (PMID 30908480, 2019). "Additionally, western blotting showed that the MICB and ULBP1 proteins in OS tumor tissues increased after DAC treatment." (PMID 29910819, 2018). "Killing may also be reinforced by the tumor cell expression of NCRs and/or NKG2D ligands (such as MICA, MICB, and ULBPs) or by antibody-dependent cell-mediated cytotoxicity (ADCC) mediated by CD16 interacting with antibody-coated tumor cells." (PMID 29163482, 2017). "Importantly, the injected tumor lesions also express genes whose protein products are the antigenic ligands for γδ T cells (BTN3A1 and MICB), and the cytokines that are the typical products of activated γδ T cells." (PMID 28424760, 2017). "In contrast, overexpression of MICB, the likewise highly enriched mRNA in the Ago complex, is considered to have a tumor-promoting rather than suppressing function." (PMID 28163933, 2017). "Besides downregulation of MHC I molecules, tumor cells can also present “induced-self” antigens including MHC class I-related sequence A (MICA) and MICB." (PMID 27843441, 2016).